KLF2 (KLF transcription factor 2)
Description:
Transcription factor that binds to the CACCC box in the promoter of target genes such as HBB/beta globin or NOV and activates their transcription. Might be involved in transcriptional regulation by modulating the binding of the RARA nuclear receptor to RARE DNA elements.
Synonyms: LKLF
Tractability: PROTAC: UniProt records ubiquitination sites on it; ubiquitination databases record sites on it.
Gene: Protein-coding gene on chromosome 19 (16,324,826 to 16,328,685, forward strand). Ensembl gene ENSG00000127528.
Subcellular location: Nucleus
Subcellular location (Human Protein Atlas): Nucleoplasm; Cytosol
Gene Ontology:
Molecular function: DNA binding; DNA-binding transcription factor activity; DNA-binding transcription factor activity, RNA polymerase II-specific; protein binding; sequence-specific double-stranded DNA binding; RNA polymerase II cis-regulatory region sequence-specific DNA binding
Biological process: cellular response to fluid shear stress; cellular response to laminar fluid shear stress; cellular stress response to acid chemical; negative regulation of sprouting angiogenesis; negative regulation of transcription by RNA polymerase II; positive regulation of DNA-templated transcription; positive regulation of nitric oxide biosynthetic process; positive regulation of protein metabolic process; positive regulation of retinoic acid receptor signaling pathway; positive regulation of transcription by RNA polymerase II; vasodilation; regulation of transcription by RNA polymerase II; cellular response to endothelin; cellular response to hydrogen peroxide; cellular response to interleukin-1; cellular response to tumor necrosis factor; negative regulation of interleukin-6 production; response to laminar fluid shear stress
Cellular component: chromatin; nucleus
Genetic constraint (gnomAD): Loss-of-function variants: 9 observed, 14.03 expected, observed/expected ratio (o/e) 0.64, 90% interval 0.39 to 1.12. The synonymous counts are far from expectation, so gnomAD's model fits this gene poorly and the ratio says little. Missense variants: 481 observed, 343.29 expected, observed/expected ratio (o/e) 1.4, 90% interval 1.3 to 1.51. Synonymous variants: 299 observed, 178.13 expected, observed/expected ratio (o/e) 1.68, 90% interval 1.53 to 1.85.
Gene-disease validity (ClinGen):
ClinGen rates the evidence that KLF2 causes each of these diseases.
pulmonary arterial hypertension (autosomal dominant): Limited. Pulmonary arterial hypertension (PAH) is a group of diseases characterized by mean pulmonary artery pressure >20 mmHg and elevated pulmonary arterial resistance leading to right heart failure.
Homologues: Orthologues: chimpanzee KLF2 (99% identical), macaque KLF2 (98% identical), dog KLF2 (97% identical), pig KLF2 (96% identical), mouse Klf2 (88% identical), rat Klf2 (88% identical), Drosophila melanogaster luna (27% identical), Drosophila melanogaster CG3065 (15% identical). Paralogues in human: KLF4 (47% identical), KLF1 (35% identical), KLF5 (29% identical), KLF7 (27% identical), KLF6 (26% identical), KLF8 (25% identical), KLF15 (25% identical), KLF12 (25% identical), KLF3 (25% identical), KLF10 (23% identical), KLF11 (23% identical), SP8 (23% identical), and 10 more.
Diseases named in the same sentence as KLF2 in open-access papers:
KLF2 is named in the same sentence as 205 diseases in open-access papers, as found by Europe PMC text mining. Sharing a sentence is not in itself a finding about the gene and the disease. The quoted sentences say what the papers report.
atherosclerosis (84 papers, 2012 to 2025). A disease characterized by the build-up of fatty material and calcium deposition in the arterial wall resulting in partial or complete occlusion of the arterial lumen. "At the molecular level, KLF-2 activation has been associated with laminar blood flow, a key protective force in the arterial walls that helps prevent atherosclerosis, since it induces a protective phenotype in endothelial cells." (PMID 36836777, 2023). "For example, interferon regulatory factor 2-binding protein 2, which attenuates macrophage-mediated inflammation and susceptibility to atherosclerosis, prevents the oxLDL-induced inflammation and EndoMT by upregulation of krüppel-like factor 2 (KLF2)." (PMID 35722128, 2022). "Kruppel-like factor 2 (KLF2) regulates endothelial cell metabolism; endothelial dysfunction is associated with hypertension and is a predictor of atherosclerosis development and cardiovascular events." (PMID 35269384, 2022). "Unsurprisingly, mice with myeloid-specific deletion of KLF2 are more susceptible to diseases such as atherosclerosis, metabolic disease, neurodegeneration, and shock." (PMID 34079826, 2021). "In support of these findings, KLF2-hemizygous mice on an Apolipidprotein-E (ApoE)-deficient background also showed increased, diet-induced atherosclerosis (Table A1)." (PMID 34696279, 2021). "For instance, both hemizygous Klf2 germline deletion or endothelial-specific Klf4 loss sensitized atheroprone apolipoprotein E–deficient (ApoE−/−) mice to high fat diet-induced atherosclerosis." (PMID 34299213, 2021). "Loss of KLF2 in DCs aggravates atherosclerosis as a result of enhanced T-cell activation and heightened inflammatory cytokine production." (PMID 29459900, 2018). "Given the inflammatory potential of KLF2 knockout macrophages, one would predict that loss of myeloid KLF2 would be associated with increased vascular inflammation and atherosclerosis." (PMID 29459900, 2018). "Monocytes from patients with atherosclerosis exhibit less Klf2 expression than healthy controls, indicating that the inflammatory state associated with low-KLF2 translates to atherosclerotic disease." (PMID 29459900, 2018). "In vivo animal experiments demonstrated that endothelial cell-specific deficiency of KLF2 predisposed to atherosclerosis development." (PMID 28751752, 2017). "It has been shown that KLF2 deficiency increased diet-induced atherosclerosis in apolipoprotein E-deficient mice." (PMID 29125549, 2017). "Hemizygous state of KLF2 (KLF2+/−) increases diet-induced atherosclerosis in apolipoprotein E-deficient mice." (PMID 28208647, 2017). "The KLF2 deficiency has been associated with chronic inflammatory diseases such as atherosclerosis, rheumatoid arthritis, Gram-positive endotoxin-induced sepsis." (PMID 29125549, 2017). "Notably, disturbed flow patterns, which are found in vascular areas predisposed to atherosclerosis, significantly reduce the endothelial expression of KLF2 and KLF4, resulting in changes in the transcriptome that exacerbate inflammation and thrombosis." (PMID 40362576, 2025). "In the condition of hypertension, KLF2 deficiency disrupts autophagy, accelerating atherosclerosis." (PMID 41373858, 2025). "However, besides KLF2/4, hemodynamic forces activate several signaling pathways to regulate endothelial phenotypes associated with atherosclerosis, via other transcription factors, such as YAP/TAZ, NRF2, HIF-1a, NF-κB and AP-1." (PMID 35883633, 2022).
atherosclerosis (continued). "Moreover, KLF2 was implicated in mast cell physiology and adipogenesis, as well as diseases such as atherosclerosis, thrombosis and lymphomas (e.g., Marginal zone B cell lymphoma)." (PMID 34696279, 2021). "Indeed, KLF2/4 expression decreases in numerous vascular disease states such as atherosclerosis, stroke, pulmonary artery hypertension, and age-associated loss of vasoreactivity." (PMID 34079826, 2021). "In addition, myeloid-specific Klf2 knockout in an atheroprone LDL receptor-deficient background (Ldl−/−) increased atherosclerosis progression." (PMID 28751752, 2017). "Endothelial KLF2/4 expression is considered a primary mechanism by which hemodynamic forces maintain homeostasis in the vasculature and prevent pathogenic states such as atherosclerosis, but whether they serve a similar role in cardiac valves is unknown." (PMID 40519164, 2025). "Therefore, the discovery of KLF2 activators in endothelial cells might prevent and treat cardiovascular diseases associated with endothelial dysfunction, such as atherosclerosis." (PMID 36362263, 2022). "Early investigations (2005–2010) established fundamental connections between DNA methylation patterns and atherosclerosis development, particularly the silencing of protective genes such as KLF2 and KLF4 through promoter hypermethylation." (PMID 40428388, 2025). "As a member of the KLF family that controls atherosclerosis-related processes, KLF2 demonstrates endothelial protection and anti-inflammatory activity." (PMID 41373858, 2025). "For instance, simvastatin upregulates KLF2 expression in ECs, enhancing Foxp1 activity to suppress vascular inflammation and inhibit atherosclerosis progression." (PMID 41373858, 2025). "Collectively, these mechanisms—distinct yet complementary to those of KLF2—highlight the multifaceted protective role of KLF4 in atherosclerosis." (PMID 41373858, 2025). "It regulates KLF2, which enhances endothelial barrier function and inhibits atherosclerosis, thrombosis, and coronary artery lesions." (PMID 40362577, 2025). "For example, chrysin counteracts the inhibitory effect of EC-derived exosomal miR-92a on Kruppel-like factor 2 (KLF2) expression to protect blood arteries from atherosclerosis." (PMID 39980588, 2025). "Current studies researching KLF2 and atherosclerosis mainly focus on two aspects: blood flow and inflammation." (PMID 41373858, 2025). "Regarding the impact of abnormal DNA methylation on inflammation and endothelial dysfunction in atherosclerosis, key protective factors such as KLF2, KLF4, and CREG exhibit anti-atherosclerotic actions." (PMID 40428388, 2025). "In a mouse atherosclerosis model, IRF2BP2-deficient macrophages exhibited pro-inflammatory traits that responded to KLF2 restoration with enhanced anti-inflammatory features." (PMID 39385609, 2024). "KLF2 activation was predicted to activate CRP, which was subsequently associated with the enhanced progression of atherosclerosis and inflammation." (PMID 39125657, 2024). "For instance, EVs secreted by endothelial cells transduced with Krüppel-like factor 2 (KLF2) protect against atherosclerosis by shifting from proinflammatory M1 to anti-inflammatory M2 macrophages." (PMID 37946271, 2023). "Researchers have identified suberanilohydroxamic acid as a potent pharmacological inducer of KLF-2, capable of repressing vascular inflammation and atherosclerosis." (PMID 36836777, 2023). "Various conditions further exacerbate the atherosclerosis risk, including hyperglycemia and high levels of low-density lipoprotein (LDL), two conditions where KLF-2 expression in endothelial cells is reduced." (PMID 37373238, 2023). "The protective effects of KLF2 in atherosclerosis make it an attractive target for the development of new treatments for cardiovascular disease." (PMID 36984888, 2023). "Vascular calcification plays an important role in the pathogenesis of atherosclerosis; thus, the role of KLF2 is of clinical interest." (PMID 36984888, 2023).
atherosclerosis (continued). "KLF2 plays a crucial role in the molecular mechanisms of atherosclerosis, regulating multiple pathways involved in endothelial cell function, inflammation, and lipid metabolism." (PMID 36984888, 2023). "Among these mechanical effects, shear stress is considered as the most important factor in atherosclerosis development through the activation of eNOS (endothelial NO synthase) via mechanosensitive transcription factor (such as KLF2 (Kruppel-like factor 2))." (PMID 37570643, 2023). "In contrast, too-low or disturbed shear stress (DSS) leads to only weak induction of KLF-2 in exposed ECs, thereby supporting the development of atherosclerosis in such vessels." (PMID 37373238, 2023). "Further in this review, we focus on the role of KLF2, one of the master regulators of the shear stress-induced gene expression in endothelial cells and the development of atherosclerosis." (PMID 35203463, 2022). "Further, we discuss several natural compounds (such as leaves extracts, flavonoids, and polyphenols) with defined mechanisms of action on KLF2 and used for atherosclerosis treatment." (PMID 35203463, 2022). "We also highlight future directions for applying repurposed drugs and natural plant-based bioactive compounds in developing novel therapeutic strategies targeting KLF2 in atherosclerosis treatment and prevention." (PMID 35203463, 2022). "Emerging studies show that KLF2 represents a promising therapeutic target for pharmacological intervention to prevent and treat atherosclerosis." (PMID 35203463, 2022). "In endothelial cells, the mechano-responsive transcription factor KLF2 is an important regulator of intravascular homeostasis and can participate in the prevention of atherosclerosis through anti-inflammatory action." (PMID 36364780, 2022). "In this review, we present a comprehensive overview of the role of KLF2 in atherosclerosis development and progression." (PMID 35203463, 2022). "Kruppel-like factor 2 (KLF2), a protective transcription factor against atherosclerosis, is expressed when the blood flows laminarly." (PMID 36093338, 2022). "Biological analyses and luciferase assays show that HUVEC-exo-RNCR3 targets the MIR-185-5P/KLF2 axis to promote the proliferation of ECs and VSMCs and plays a protective role in the development of atherosclerosis." (PMID 34307511, 2021). "For example, exo-MIR143/MIR145 secreted by endothelial cells expressing KLF2 can communicate with smooth muscle cells, increase the expression of dedifferentiation-related genes, and reduce atherosclerosis in ApoE-/- mice." (PMID 34307511, 2021). "Extracellular microvesicles containing miR-143-3p secreted by l-flow or KLF2 overexpressed in endothelial cells inhibits atherosclerosis in adjacent VSMCs." (PMID 34150863, 2021). "Kruppel-like factor 2 (KLF2) is a shear stress-induced transcription factor with protective effects against atherosclerosis." (PMID 34513963, 2021). "Kruppel-like factor 2 (KLF2) is one of the critical anti-inflammatory mediators in atherosclerosis in ECs, which is also the transcriptional factor of NOS." (PMID 34976029, 2021). "Montelukast was previously reported to activate KLF2 expression in the treatment of atherosclerosis." (PMID 34565285, 2021). "Inflammatory molecular lipopolysaccharides (LPS) regulate the expression of KLF2 through DNA hypermethylation, and this discovery provided a novel perspective to atherosclerosis." (PMID 34976029, 2021). "Enhancing KLF2 expression and activity improves endothelial function, controls multiple genes critical for inflammation, and prevents atherosclerosis." (PMID 32669659, 2020). "The transcription factor KLF2 (Kruppel like factor 2), which suppress an inflammatory activation, a feature missing in atherosclerosis-prone areas and characterized by a disturbed blood flow, is induced by arterial shear forces." (PMID 31500313, 2019).
atherosclerosis (continued). "We also found that exosomal miR-25 regulates inflammatory factors in the endothelial cells by targeting KLF2, a repressor of vascular inflammation and atherosclerosis." (PMID 31750260, 2019). "The protective roles of KLF2 and KLF4 have been demonstrated in experimental models of atherosclerosis (ApoE-deficient and LDL receptor-deficient mice), where deficiency of KLF2 and KLF4 accelerates the process." (PMID 31354915, 2019). "This is, indeed, the case as mice with myeloid-specific KLF2 deletion on the Apoe−/− background exhibit increased atherosclerosis with increased vascular oxidative stress." (PMID 29459900, 2018). "In conclusion, endothelial MIF and KLF2 play a critical role in the initiation and progression of atherosclerosis." (PMID 29403061, 2018). "KLF2 expression was significantly decreased in monocytes of the patients with atherosclerosis, a chronic low-grade inflammatory disease, characterized by higher expression of FOS (osteosarcoma gene)." (PMID 29125549, 2017). "KLF2 is a transcription factor studied extensively in atherosclerosis and fibrosis, and previous studies of KLF2 signaling showed TSP1 and PAI1 (plasminogen activator inhibitor-1) to be two of its most strongly affected targets." (PMID 29322934, 2017). "The ceRNA regulatory network, RNCR3/miR-185-5p/KLF2, would provide a novel insight into gene regulatory network in atherosclerosis." (PMID 27253412, 2016). "In contrast to the atheroprotective effects of shear stress and KLF2 expression, intimal inflammation is a driving force in the pathology of atherosclerosis." (PMID 26717516, 2015). "ENOS and COX2 are vasodilators that play an important role in homeostasis; KLF2 is a transcriptional factor which is more abundant in the high-shear regions resistant to atherosclerosis than in areas of disturbed flow and endothelial dysfunction." (PMID 26147292, 2015). "In mice, genetic deficiency of either KLF2 or KLF4 in ApoE-/- mice (which develop atherosclerotic lesions when placed on high fat diet) enhances atherosclerosis, indicating an atheroprotective role for KLF2 and KLF4." (PMID 25540650, 2014). "Kruppel-like factor 2 (KLF2) is a shear-responsive transcription factor believed to be atheroprotective by preventing the formation of atherosclerosis." (PMID 25429310, 2014). "In atherosclerosis, metformin could increase the expressions of KLF2 and nuclear erythroid-related factor 2 (Nrf2)." (PMID 40663175, 2025). "However, ox-LDL exposure significantly downregulates KLF2 expression, counteracting this protective effect and promoting atherosclerosis." (PMID 40861271, 2025). "PH exerts a therapeutic effect against HG-induced endothelial cell dysfunction and decreases the acceleration of atherosclerosis in diabetic mice treated at a dose of 20 mg/kg through the upregulation of nitric oxide synthase (eNOS) and kruppel-like factor 2 (KLF2) expression." (PMID 39062722, 2024). "On the other hand, key pro‐atherosclerotic genes including klf2 (Kruppel‐like factor 2), sele (E‐selectin), or fos (which is critical for foam cell formation and atherosclerosis) all had identifiable H3K9me3 peaks and thus were repressed in DMSO treated cells only." (PMID 38145971, 2024). "The results of these studies suggest that increasing KLF2 expression may be a novel strategy for preventing and treating atherosclerosis." (PMID 36984888, 2023). "KLF2 also modulates the inflammatory response in atherosclerosis." (PMID 36984888, 2023). "In addition, studies on statin lipid-lowering drugs and resveratrol have confirmed that they can up-regulate the expression of KLF2, play anti-coagulation, anti-atherosclerosis, and other effects, and protect the function of vascular ECs." (PMID 37077343, 2023). "While KLF2 is expressed at high levels in endothelial cells in the area of laminar flow, its expression drops to low levels near the sites of blood flow disturbances, which are characterized by the development of atherosclerosis." (PMID 36984888, 2023).